INS (insulin)
Diseases named in the same sentence as INS in open-access papers (continued):
Sharing a sentence is not in itself a finding about the gene and the disease.
myocardial infarction (continued). "Multivariable analysis using logistic regression was performed adjusting for the following variables: age, gender, prior myocardial infarction, and chronic administration of aspirin, clopidogrel, insulin, oral hypoglycemic agents, beta-blockers and calcium channel blockers." (PMID 23369699, 2012). "Intensive insulin therapy improved survival in diabetic patients with acute myocardial infarction." (PMID 20137090, 2010). "For example, Latin America has had an active participation in the MRC CRASH Trial, which evaluated the effect of corticosteroids on head injury, or the CREATE-ECLA trial, which evaluated the effect of the glucose-insulin-potassium (GIK) infusion in patients with myocardial infarction." (PMID 18301772, 2008). "Indeed, this was the basis for some of the earliest studies of the cardioprotective effects of insulin in the 1960s/1970s, demonstrating that glucose-insulin-potassium (GIK) treatment protects the myocardium from ischaemic damage in a dog model of myocardial infarction." (PMID 35766350, 2022). "In children, corticosteroids increased the use of insulin but did not significantly influence the risk of myocardial infarction, which may be related to neonatal cardiomyocytes having increased glucose uptake and utilization." (PMID 35722531, 2022). "Furthermore, another study showed that intensified insulin-based glycemic control had a long-term impact on life expectancy, with an average survival increase of 2.3 years and lasting at least 8 years in DM patients with acute myocardial infarction." (PMID 33598483, 2021). "However, the risk of nonfatal myocardial infarction and stroke was significantly increased by insulin treatment, whilst metformin was protective." (PMID 30402502, 2018). "Interestingly, myocardial infarction induced by artery ligation in nondiabetic rats causes a partial impairment of insulin response that is associated with cardiac contractile dysfunction." (PMID 22347652, 2011). "Almost all studies of cardioprotection with insulin and IGF1 have used models of myocardial infarction with cardiomyocytes or the heart subjected to hypoxia/ischaemia followed by reoxygenation/reperfusion." (PMID 35766350, 2022). "In addition, low-dose corticosteroids significantly reduced the mechanical ventilation time without increasing the risks of myocardial infarction and insulin infusion, while high-dose corticosteroids were associated with increased risks of myocardial infarction and prolonged mechanical ventilation." (PMID 35722531, 2022). "In contrast, studies using a fixed glucose-insulin-potassium (GIK) regime, with acute myocardial infarction, to promote a switch away from myocardial fatty acid metabolism to glucose metabolism, were approximately 0.1 - 1 iU/kg/hr; 30 - 80 g glucose/hr)." (PMID 34220705, 2021). "It was shown that insulin and pterostilbene protected against MI/RI by blocking ONOO−-triggered oxidative/nitrative stress and that they both improved cardiac functions, as well as reduced myocardial infarction, apoptosis, and creatine kinase/lactate dehydrogenase release." (PMID 34055195, 2021). "The results of the study proved, firstly, that intensive insulin treatment regimens result in improvement in metabolic control and significant reduction in IMT and all vascular complications rates, CVD, and myocardial infarctions among them." (PMID 32793113, 2020). "During myocardial infarction, SH groups, IGF-1, insulin, hsCRP, and PSP were significantly different when compared to the control group." (PMID 31540292, 2019). "Adjusted hazard ratios (95% CI) of developing myocardial infarction in patients receiving sulfonylurea, meglitinides or TZD with insulin treatment as the reference and subgroup analyses." (PMID 27513562, 2016). "Exercise for 8 weeks following myocardial infarction not only increased the activities of PI3K, Akt, and eNOS, but also elevated phosphorylation of PI3K, Akt, eNOS, and NO production by insulin." (PMID 25907785, 2015).
myocardial infarction (continued). "In addition, two recent North American cohorts have shown that diabetic subjects treated with insulin compared with those not treated with insulin are at higher risk of myocardial infarction and mortality (cardiovascular, non-cardiovascular and all-cause mortality)." (PMID 24752580, 2014). "Long-term insulin treatment did not improve survival in type 2 diabetic patients following myocardial infarction." (PMID 38172896, 2024). "It was more frequent in non-lacunar versus lacunar acute IS, non-ST segment elevation versus ST-segment elevation acute myocardial infarction, and insulin-treated versus non-insulin-treated DM." (PMID 38999223, 2024). "Insulin has potent cardioprotective effects, particularly in the context of ischaemia with or without reperfusion, as occurs with myocardial infarction." (PMID 35766350, 2022). "In non-diabetic rats, myocardial infarction induced by artery ligation leads to a partial impairment of insulin response." (PMID 33267804, 2020). "Transient non-severe increased insulin requirement in patients hospitalized for medical conditions such as sepsis or myocardial infarction is a well-known phenomenon." (PMID 33066762, 2020). "Transient non-severe increased insulin requirement in patients hospitalized for various medical conditions such as sepsis or myocardial infarction is a well-known phenomenon with insulin doses usually not exceeding 5–10 Units/hours." (PMID 33066762, 2020). "Because hyperglycaemia is associated with poorer outcome in the setting of acute myocardial infarction, numerous studies have investigated the cardioprotective effect of insulin in patients with acute myocardial infarction with and without diabetes mellitus." (PMID 31430831, 2020). "Metformin should also be withdrawn in people at risk of tissue hypoxia or deterioration in renal function, such as those with acute heart failure or recent myocardial infarction, whereas there are no such barriers to receiving insulin as monotherapy." (PMID 27152598, 2016). "The fully adjusted model included age, smoking status, gender, income, BMI, born in the USA, vigorous physical activity, travel on highway, cooked with oil, non-workday time spent inside home, insulin medication, statin medication, heart attack." (PMID 24090339, 2013). "The potential of insulin to mitigate against this hyperglycemic effect on myocardial ischemia/reperfusion injury is currently unclear, although clinical trials of glucose-insulin-potassium (GIK) therapy for acute myocardial infarction are certainly relevant." (PMID 24371503, 2013). "Likewise interactions between glucose, insulin and potassium as they are presumed to occur with the administration of GIK (glucose-insulin-potassium) in acute myocardial infarction, can better be studied with a system such as GRIP-II." (PMID 20100342, 2010). "Raz 2005 reported two cases of myocardial infarction in the insulin monotherapy group which were not considered to be treatment-related." (PMID 19568428, 2009). "On the other hand, the I/R-induced myocardial infarction (MI) was not attenuated by insulin treatment." (PMID 19706162, 2009). "In conclusion, our study identified miR-199a-5p could promote the progression of myocardial fibrosis after myocardial infarction by targeting GSK-3β, which plays an important role in the insulin signaling pathway, which provides novel targets for diagnosis and treatment of MF." (PMID 36788811, 2023). "This may provide longer term cardioprotection, but seems unlikely to account for acute protection afforded by insulin in models of myocardial infarction." (PMID 35766350, 2022). "Additionally, the rs7242 G allele was associated with an increased risk of myocardial infarction in nonsmoker populations and with increased serum insulin levels in myocardial infarction patients." (PMID 31268630, 2019).
myocardial infarction (continued). "Moreover, insulin administration did not decrease the myocardial infarction area of the CoCl2+ SPC group (24.87 ± 4.11% vs. 25.91 ± 3.03%, P > 0.05)." (PMID 28659817, 2017). "Therefore, lifestyle interventions that improve insulin sensitivity in aortas, such as physical activity, may have significant value in the prevention and treatment of myocardial infarction and its complications in MI patients." (PMID 25907785, 2015). "However, initial promise with glucose-insulin infusions immediately after myocardial infarction, could not be confirmed in later studies and an approach with insulin-treatment may even cause early harm after STEMI." (PMID 38184612, 2024). "However, recent study reported that short-term insulin treatment (48 hours) normalized blood glucose concentration but neither reduced myocardial infarct size nor restored the cardioprotective effects of sevoflurane post-conditioning in STZ-induced diabetic rats." (PMID 23991188, 2013).
cognitive decline (305 papers, 2006 to 2026). "Individuals with type 2 diabetes (T2D), characterized by impaired insulin action and enhanced glucagon secretion (hyperglucagonemia), resulting in hyperglycemia, have a higher risk of cognitive decline." (PMID 40271226, 2025). "Insufficient insulin uptake appears to be the main trigger for neurodegenerative mechanisms, particularly in the hippocampus, where insulin resistance induces cognitive decline associated with neurodegeneration." (PMID 40144552, 2025). "Through a range of behavioral, molecular, and cellular analyses, we confirmed that elevated C3 expression leads to cognitive decline, synaptic and neuronal loss, astrocytosis, insulin signaling impairment in astrocytes, and mitochondrial dysfunction." (PMID 40539508, 2025). "This review aims to elucidate the potential connections between insulin resistance and cognitive decline while also proposing interventions to slow aging and reduce the risk of early cognitive decline." (PMID 41294899, 2025). "Glucose metabolism is critical in neurodegenerative diseases such as AD, as impaired insulin signaling and glucose utilization in the brain have been linked to cognitive decline." (PMID 39984825, 2025). "IR, defined as reduced sensitivity to insulin, has repeatedly been proposed as a major risk factor for cognitive decline." (PMID 40869398, 2025). "Insulin therapy, by improving metabolic control, has also been linked to slower PD progression and cognitive decline." (PMID 40869398, 2025). "This review provides an overview of BACE1 mechanism as a dual disease-modifying therapeutic target to mitigate β-amyloidosis and insulin resistance that underlie cognitive decline at the intersection between AD and DM." (PMID 41446639, 2025). "The objective of this study was to examine the association of postmortem brain insulin signaling with late-life cognitive decline." (PMID 38029396, 2024). "Impairment in brain insulin signaling has been consistently linked to cognitive decline in animal models and humans." (PMID 38988328, 2024). "In this community-based clinical-pathologic cohort study, we found associations between brain insulin signaling and late-life cognitive decline." (PMID 38029396, 2024). "Disrupted insulin signaling and its associated inflammation are potential triggers of neurodegenerative changes that lead to cognitive decline." (PMID 39408069, 2024). "In conclusion, these findings provide novel evidence for an association between brain insulin signaling and late-life cognitive decline." (PMID 38029396, 2024). "This suggests a link between neuroinflammation and insulin signaling in the hippocampus as a physiopathological mechanism underlying the connection between insulin resistance and cognitive decline." (PMID 39456952, 2024). "Building on our previous work, we sought to examine the association between brain insulin signaling and late-life cognitive decline." (PMID 38029396, 2024). "Previous clinical work associates the loss of muscle mass with a proinflammatory state, insulin resistance, and cognitive decline." (PMID 36672646, 2023). "The purported molecular mechanisms that connect loss of muscle mass with cognitive decline include altered myokine secretion, inflammation, insulin resistance, abnormal protein accumulation, oxidative stress, and mitochondrial dysfunction." (PMID 35661882, 2022). "Impaired hippocampal insulin signaling is linked to memory deficits and cognitive decline in AD models and in patients." (PMID 33911072, 2021). "The reduction of brain insulin sensitivity is one of the most well-known causes of HFD-induced cognitive decline." (PMID 33916835, 2021). "Recent studies have also confirmed the similarities between the changes seen in ZDF rats and brain samples from people with AD, namely, Aβ accumulation and insulin resistance in the brain causing neuronal injury and ultimately cognitive decline." (PMID 34485269, 2021).
cognitive decline (continued). "Abnormal serine phosphorylation of IRS1, which, when co-localized with neurofibrillary tangles, hinders the actions of insulin and is associated with cognitive decline." (PMID 33100956, 2020). "It was reported that protective neurotrophic factor, growth hormone and risk factors, inflammation, insulin resistance, and oxidative stress, for cognitive decline were increased and decreased in the elderly with frail or sarcopenia, respectively." (PMID 32737350, 2020). "Yet, insulin insensitivity has been linked to memory deficits, cognitive decline, and many of the characteristic symptoms that have been displayed in AD." (PMID 32365816, 2020). "Such an impairment of insulin signaling exacerbates neurodegenerative changes and synaptic loss, which ultimately leads to cognitive decline." (PMID 33013281, 2020). "Impaired brain insulin signaling has been consistently associated with cognitive decline in animal models and in humans." (PMID 30804755, 2019). "In humans, DGKB has been associated with stimulating the secretion of insulin, a hormone found to have potent effects in the brain, with insulin dysfunction underlying several risk factors implicated in cognitive decline." (PMID 25860228, 2015). "Impaired brain insulin signalling has been linked to AD, with increased IR being additionally demonstrated to be associated with synaptic failure, brain atrophy, and cognitive declines." (PMID 26692280, 2015). "In conclusion, the increased tyrosine phosphorylation of IRS-1 enhances insulin signal transduction in modulating of neurotransmitters associated with cognitive function and alleviating cognitive decline in brain." (PMID 24481061, 2014). "This would contribute to better insulin signaling in the brain and, therefore, a slowing of cognitive decline associated with brain insulin resistance." (PMID 23320146, 2012). "It is clear from this review that hyperinsulinemia is one of the most frequent endocrine features in overweight people leading to insulin desensitization and represents a risk factor for cognitive decline." (PMID 22761616, 2012). "One of the two studies examining the association of insulin use and risk of cognitive decline suggested a positive association." (PMID 19127292, 2009). "This review identifies metabolic reprogramming as an important driver of DE cognitive decline and linked the major pathologic processes: brain insulin resistance, oxidative stress, defective autophagy, and dysregulated glycolysis/lipolysis, all of which contribute to accelerated brain aging." (PMID 41332987, 2025). "In AD, there is a general alteration in metabolism, with changes in short-chain fatty acid (SCFA) and bile acid levels, as well as dysregulation of glucose metabolism and cerebral insulin resistance, which have been implicated in cognitive decline and amyloid accumulation." (PMID 40243365, 2025). "With that said, if unintentional weight loss were a side effect of intranasal insulin prescribed to treat cognitive decline, it could be a significant concern." (PMID 40980544, 2025). "High-intensity activity may also interfere with insulin sensitivity, increasing the risk of glucose metabolism abnormalities, which are significantly associated with cognitive decline." (PMID 40255385, 2025). "Diabetes-associated cognitive decline may have multiple underlying mechanisms, including vascular abnormalities and changes in glucose, insulin sensitivity, and amyloid metabolism." (PMID 39883521, 2025). "Previous research has suggested several potential mechanisms by which brain insulin signaling could be linked to cognitive decline." (PMID 38029396, 2024). "Consistent with this hypothesis, recent evidence has linked late-life cognitive decline to increased phosphorylation of the serine/threonine kinase (AKT)—a marker of brain insulin resistance—in the prefrontal cortex." (PMID 39656485, 2024).